MMP3 (matrix metallopeptidase 3)
Diseases named in the same sentence as MMP3 in open-access papers (continued):
Sharing a sentence is not in itself a finding about the gene and the disease.
squamous cell carcinoma (14 papers, 1999 to 2026). A carcinoma arising from squamous epithelial cells. "For example, in squamous cell carcinoma, the initial tumor growth rates of wild-type mice expressing MMP3 were lower than that of knockout mice." (PMID 37609436, 2023). "The SWCNTs was modified with an antibody for matrix metalloproteinase-3 (MMP-3) as a biomarker for squamous cell carcinoma and adrenal tumors." (PMID 28672780, 2017). "MMP3 has been shown to decrease initial growth rates of squamous cell carcinoma in wild type mice compared to knockouts." (PMID 21170377, 2010). "An expression of MMP-1 (interstitial collagenase), MMP-2 (72-kDa type IV collagenase) and MMP-3 (stromelysin-1) was investigated in squamous cell carcinoma (SCC) and its precancerous condition, actinic keratosis (AK), using in situ hybridization techniques." (PMID 10362121, 1999). "HIF1A and MMP3: Previous studies have highlighted their roles in promoting invasion and metastasis in other squamous cell carcinomas or skin tumors, this study for the first time links both genes to the PI3K/AKT/mTOR signalling pathway and validates their expression changes via qPCR." (PMID 41438693, 2026). "In addition, over-expression of matriptase, a protease that has been suggested to be an upstream activator of MMP3, induces squamous cell carcinoma in the skin." (PMID 19142229, 2009). "Likewise, squamous cell carcinoma induced in MMP-3 null mice grew more rapidly than tumours in control animals." (PMID 17311017, 2007). "Our microarray analysis did not identify any differences in MMP3 gene expression between stromal cells derived from ADC and normal lung, at odds with a previous study in which an increased MMP3 gene expression in ADC and squamous cells carcinoma was observed." (PMID 33905434, 2021). "In 1998, the results of a study comparing OLP, dysplasia and squamous cell carcinoma (SCC) revealed that MMP-1, MMP-2, and MMP-3 expression were lower in OLP than SCC, and MMPs and TIMPs were clearly upregulated during invasion in oral SCC." (PMID 22737547, 2012).
inflammatory bowel disease (12 papers, 2019 to 2025). A spectrum of small and large bowel inflammatory diseases of unknown etiology. "Literature data indicate that the main biomarkers of inflammatory bowel diseases are four MMPs, i.e., MMP-3, MMP-7, MMP-9, and MMP-11." (PMID 38203373, 2023). "Scientists have confirmed that MMP-3 is a promising marker of inflammatory bowel diseases." (PMID 38203373, 2023). "MMP3 is upregulated in the intestine in inflammatory bowel disease and may play an important role in tissue remodeling and destruction." (PMID 36072482, 2022). "For example, patients with inflammatory bowel disease show upregulation of MMP9 in their inflamed intestinal tissue, which may contribute to fibrotic remodeling of the gut mesenchyme; and MMP3 plays key roles in branching morphogenesis in tissues such as the breast." (PMID 38779415, 2024).
knee osteoarthritis (12 papers, 2011 to 2025). "The objective is to investigate the clinical benefits of fire acupuncture and warming therapy for managing knee osteoarthritis of the cold-dampness subtype, while also examining the treatment’s effects on interleukin-1β (IL-1β) and matrix metalloproteinase-3 (MMP-3) in the serum." (PMID 40493319, 2025). "In fact, a recent study has identified a significant elevation of serum MMP‐3 level in patients with knee osteoarthritis and indicates that this level may serve as a prognostic marker for cartilage destruction." (PMID 34078001, 2021). "Experiments in a rat model of knee osteoarthritis have demonstrated that increased caspase‐3 and MMP‐3 expression results in increased apoptosis of chondrocyte, whereas decreased caspase‐3 and MMP‐3 expression results in significantly improved symptoms of knee osteoarthritis." (PMID 33304230, 2020). "Our results suggest that serum levels of MMP3 could be used as a potential biomarker for knee osteoarthritis and possible disease predictor, using a simple blood test." (PMID 29904905, 2018). "Our results suggest that serum levels of MMP3 could be used as a potential biomarker for knee osteoarthritis, using a simple blood test." (PMID 29904905, 2018). "Our hypothesis is that there is a significant difference in MMP-3 and GAG levels between the operated and non-operated knees which correlates with their serum levels, potentially allowing their use as biomarkers in tracking disease progression in this model of knee osteoarthritis." (PMID 29904905, 2018).
periodontal disease (12 papers, 2012 to 2025). "The authors reported that higher MMP-3 and TIMP-1 levels correlated positively with clinical parameters and were related to significantly greater risk of progression of periodontal disease." (PMID 36167610, 2023). "The present study found that NSPT resulted in reductions of salivary MMP-3, -8, and -9, and identified the potential of MMP-3 as a biomarker in the diagnosis of periodontal disease." (PMID 35562715, 2022). "MMP-3 as a biomarker for the diagnosis of periodontal disease was identified, with a predictive sensitivity and specificity of 81.8% and 55.5%, respectively." (PMID 35562715, 2022). "Compared with healthy participants, the patients with periodontal disease showed increased concentrations of salivary MMP-3, -8, and -9." (PMID 35562715, 2022). "The predictive factors of MMP-3, -8 and -9 as biomarkers for diagnosis periodontal disease were likewise analyzed with an ROC curve." (PMID 35562715, 2022). "The study findings showed statistically significant decreases in salivary MMP-3, -8, and -9 concentrations in patients with periodontal disease 3 weeks after NSPT initiation." (PMID 35562715, 2022). "Compared with healthy participants at baseline, the periodontal disease group also showed higher salivary MMP-3, -8, and -9 concentrations." (PMID 35562715, 2022). "In the present study, the up-regulation of MMP-3 was observed after IL-12 treatment, which possibly contributes to progression of periodontal disease." (PMID 29054963, 2017). "Especially, MMP-1 and MMP-3 are important in periodontal diseases." (PMID 34504537, 2021). "MMP-1 (collagenase I) and MMP-3 (stromelysin) play important roles in periodontal diseases." (PMID 34504537, 2021). "Research reported that relatively low MMP-3 levels in gingival crevicular fluid raise the question of whether there is enough sensitivity and specificity for this biochemical marker to evaluate periodontal disease progression." (PMID 36167610, 2023). "Therefore, inhibition of MMP-1 and MMP-3 production leads to the treatment of periodontal disease." (PMID 34066937, 2021). "This suggests that MKE might have potential to treat periodontal disease by inhibiting collagenases (MMP-1, -8, -13), gelatinase (MMP-9), and stromelysin (MMP-3)." (PMID 36661522, 2023). "In addition, it was reported that there is a substantial increase in the concentrations of MMP-3 and decrease of TIMP-1 in gingival crevicular fluid (GCF) in periodontal disease." (PMID 29054963, 2017).
aneurysm (11 papers, 2004 to 2023). Bulging or ballooning in an area of an artery secondary to arterial wall weakening. "In the next step, we inspected the expression of other MMPs, MMP2 and MMP3, known to play a role in aortic wall degradation during aneurysm formation." (PMID 32617140, 2020). "We suppose that increased collagen turnover results from the overactivity of metalloproteinases, possibly MMP2 and MMP3, both previously reported as crucial in the aneurysm formation." (PMID 32617140, 2020). "Expression of MMP-3 in the ascending thoracic aortic wall has been shown to correlate inversely to the elasticity of the wall, with reduced elasticity potentially leading to aneurysm formation." (PMID 37958625, 2023). "Conversely, given the relatively straightforward correlation of aneurysm incidence with MMP3 and TIMP1 level, we suppose that these may be the key players in the aortic remodeling upon high-dose AngII." (PMID 33467682, 2021). "Notably, MMP3 activity is essential for the development of AngII-induced aneurysms, and it is strongly reduced in AngII-treated HO-1 KO mice." (PMID 33467682, 2021). "New medical therapeutic options targeted specifically against MMP-3 may prove useful in the prevention of aneurysm formation." (PMID 15482602, 2004). "Reduced aneurysm formation has been observed in mice with MMP-3 gene inactivation." (PMID 15482602, 2004). "Based on these and our own observations, we maintain that MMP-3 over-expression may occur in aneurysm segments." (PMID 15482602, 2004). "Assessment of spontaneous AAA formation in long-term high fat-fed Apoe−/− mice with and without Mmp3-deficiency revealed increased presence of aneurysms in Mmp3 wild-type mice, as characterised by elastin fragmentation, aortic wall thinning, and rupture of medial elastin fibres." (PMID 37799778, 2023). "Increased levels of MMP-2, MMP-3, MMP-9 and MMP-12 have been identified in aneurysm vessel walls." (PMID 15482602, 2004). "Therefore, the sharp decrease of MMP-3 levels during the first days after SAH might be attributable to increased consumption of coagulatory factors, triggered by aneurysm rupture." (PMID 23555845, 2013).
ankylosing spondylitis (11 papers, 2008 to 2025). An autoimmune chronic inflammatory disorder characterized by inflammation in the vertebral joints of the spine and sacroiliac joints. "For clinic, elevated MMP3 has been reported in patients with ankylosing spondylitis, a chronic inflammatory disease, compared with healthy controls." (PMID 36684250, 2022). "For example, active serum MMP3 levels decreased in both ankylosing spondylitis (AS) and RA after anti-TNFα treatment." (PMID 32782251, 2020). "Recently, the serum concentrations of both MMP-3 and MMP-9 have been found to be associated with disease activity in ankylosing spondylitis." (PMID 24490631, 2014). "High levels of MMP-3 have been shown in serum of ankylosing spondylitis patients compared to controls." (PMID 24078814, 2013). "Circulating MMP-3 levels were also reduced by TNF-α-blocker treatment in ankylosing spondylitis, and there was a correlation between changes in MMP-3 and changes in disease activity during treatment." (PMID 19968600, 2009). "Serum MMP-3 levels were found to be twice as high in ankylosing spondylitis patients than in controls, and showed a positive correlation with disease activity." (PMID 19968600, 2009). "Therefore, this review can and should be positioned as a pioneering contribution that proposes MMP-3 as a key molecular link between two clinical entities traditionally addressed separately: ankylosing spondylitis and acute coronary syndrome." (PMID 40277922, 2025). "Previous investigations through observation have found that matrix metalloproteinase-3 (MMP-3) has benefits for ankylosing spondylitis (AS) but it is uncertain whether there is a true positive causal connection." (PMID 39889180, 2025). "MMP-3 performs a crucial role in the pathogenesis of ankylosing spondylitis and RA." (PMID 37259429, 2023). "In ankylosing spondylitis (AS), chronic inflammation triggers a cascade of pro-inflammatory cytokines, such as tumor necrosis factor-alpha (TNF-α) and interleukin-17 (IL-17), which drive the expression of MMP-3." (PMID 40277922, 2025). "This study found higher levels of both MMP-3 and TIMP-1 in ankylosing spondylitis." (PMID 24078814, 2013).
fibrosis (11 papers, 2016 to 2024). the formation of excess fibrous connective tissue in an organ or tissue in a reparative or reactive process. "The concentration of MMP-3 was also significantly enhanced in the group of patients with advanced fibrosis." (PMID 35529854, 2022). "Bleomycin-induced fibrosis mouse model shows an increase in MMP-3 lung levels in comparison with control and mmp3-null mice protected from bleomycin." (PMID 35805895, 2022). "The concentration of MMP-3 was also significantly higher in the group of patients with advanced fibrosis 103.1 ± 73.9 ng/mL vs 69.9 ± 68.7 ng/mL, p < 0.001." (PMID 35529854, 2022). "In the groups with advanced fibrosis we found more patients with increased concentrations of MMP-3." (PMID 35529854, 2022). "Additionally, the MMP-1 and MMP-3 secreted by senescent cells during oral submucosal fibrosis have been shown to promote fibrosis in the advanced stages." (PMID 36275775, 2022). "Fibrosis involves the secretion of a series of fibrosis-related maker proteins, including collagen I, α-smooth muscle actin (α-SMA), MMP3, ECM-degrading protein and TIMP-1, which exhibit a direct role in the fibrogenesis." (PMID 34456904, 2021). "In fibrosis mice, consistently, the expression of genes related to ECM accumulation (TIMP1, MMP3 and MMP8) were decreased and genes involved in ECM elimination (MMP2, MMP9 and MMP13) were notably upregulated after JT003 treatment." (PMID 33199780, 2020). "Interestingly, elevated MMP3 expression has been observed in patients with primary biliary cholangitis (PBC), a chronic cholestatic liver disease that often progresses to cholestasis, fibrosis, cirrhosis, and liver failure." (PMID 37603094, 2023).
osteoporosis (11 papers, 2014 to 2025). A condition of reduced bone mass, with decreased cortical thickness and a decrease in the number and size of the trabeculae of cancellous bone (but normal chemical composition), resulting in increased fracture incidence. "Importantly, MMP-3 has been shown to be an important regulator of the action of sex hormones, which is associated with the pathogenesis of osteoporosis." (PMID 39407715, 2024). "In osteoporosis, dysregulation of the MMP3–OPN–MAPK pathway can lead to increased bone resorption and decreased bone formation." (PMID 40129470, 2025). "Researchers studying the serum of patients with osteoporosis found that Jintiange capsules inhibited the κB inhibitor signaling pathway by downregulating the overexpression of osteopontin, ultimately reducing MMP-3 expression." (PMID 40977787, 2025). "Curculigoside is likely to treat osteoporosis through targets such as MMP3, MMP9, IL-6, and caspase-3, acting on signaling pathways including Rap1 and TNF." (PMID 40917365, 2025). "In RA patients in the group with osteoporosis and osteopenia, MMP-3 was significantly elevated in serum compared to RA patients with a normal BMD." (PMID 38138968, 2023). "In the group of women with osteoporosis, MMP-3 levels correlated negatively with BMD and OPG ligand (OPGL), and positively with OPG and osteopontin (OPN)." (PMID 38138968, 2023). "The down-regulation of MMP-3 alleviates osteoporosis and destruction of cartilage and bone by decreasing the release of inflammatory cytokines and by regulating abnormal matrix degradation and angiogenesis." (PMID 25225501, 2014). "This study suggests that phytol-micelles may mitigate osteoporosis by restoring the balance of bone formation and resorption and activating the MMP3–OPN–MAPK pathway." (PMID 40129470, 2025). "According to several studies, MMP-3 is involved in the production of inflammatory cytokines and in osteoporosis and regulates bone destruction; therefore, MMP-3 may be responsible for delayed fracture healing." (PMID 37242557, 2023). "To sum up, we demonstrated that EV may prevent osteoporosis by reversing the imbalance of bone formation/bone resorption and activating MMP3-OPN-MAPK pathway signal." (PMID 30805367, 2019). "In this study, the downregulation of IL-6, TNF-α, IL-1β, MMP3, MMP9, and caspase-3 by curculigoside aligns with previous findings that these factors mediate osteoblast injury and extracellular matrix degradation in osteoporosis." (PMID 40917365, 2025). "In addition, MMP3 levels were higher in RA patients with osteoporosis than among patients with osteopenia, but the authors did not assess the level of statistical significance for these groups." (PMID 38138968, 2023). "Among patients with SLE, serum MMP-3 was negatively correlated only with the BMD of the lumbar spine, but not of the femoral neck, while, among patients with osteoporosis secondary to ankylosing spodylitis, it was correlated positively with TRACP-5b and negatively with BALP and VDR." (PMID 38138968, 2023).
Parkinson disease (11 papers, 2008 to 2025). A progressive degenerative disorder of the central nervous system characterized by loss of dopamine producing neurons in the substantia nigra and the presence of Lewy bodies in the substantia nigra and locus coeruleus. "Parkinson's disease, which ordinarily begins in late life, has been reported to be associated with aberrant expression of MMP-3 and MMP-9." (PMID 35444067, 2022). "Parkinson's disease has been associated with aberrant expression of MMP-3 and MMP-9." (PMID 35444067, 2022). "The present study shows that matrix metalloproteinase-3 (MMP-3) participates in degeneration of nigrostriatal dopaminergic neurons in the MPTP model of Parkinson's disease by neuroinflammation-mediated BBB disruption and infiltration of T leukocytes." (PMID 23853428, 2013). "Interestingly, MMP-3 is elevated in rat brains exposed to 6-hydroxydopamine or 1-methyl-4-phenyl-1,2,3,6-tetrahydropyridine, two classical models of parkinsonism." (PMID 35573838, 2022). "Importantly, it was demonstrated that the released and proteolytically activated MMP-3 acts as signaling molecule to activate microglia, which in turn might play a role in exacerbating degenerative human brain disorders, such as Parkinson's disease." (PMID 18629001, 2008). "In Parkinson’s disease patients, SATB1 (a CDKN1A inhibitor) levels are reduced in the substantia nigra, while CDKN2A, MMP3, IL-6, IL-1α, and CXCL8 levels are elevated, indicating an increased aging burden." (PMID 39963130, 2025).
psoriasis (11 papers, 2015 to 2025). An autoimmune condition characterized by red, well-delineated plaques with silvery scales that are usually on the extensor surfaces and scalp. "Moreover, the plasma level of MMP-3 in psoriasis patients (both PsV and PsA) was more than twice as high as in the control group." (PMID 34691360, 2021). "MMP-3 and M-CSF were found to be biomarkers for the presence of psoriasis in psoriatic disease and could potentially be used to screen for PsA in patients with psoriasis." (PMID 30229387, 2018). "The authors found higher levels of highly sensitive CRP (hsCRP), osteoprotegerin (OPG), and MMP-3 in patients with psoriasis and psoriatic arthritis as compared to patients with psoriasis alone and concluded that these could be biomarkers for psoriatic arthritis in patients with psoriasis." (PMID 29619128, 2018). "Keratinocytes can also produce a variety of matrix metalloproteinases (MMPs), such as MMP2, MMP3, and MMP9, which are involved in the inflammatory responses, cell migration, and angiogenesis in psoriasis." (PMID 36555642, 2022). "Positive correlations between MMP-3 level and proinflammatory cytokines IL-12p/70, IL-17A, and TNF-α recognized in our study confirm MMPs and Th1 and Th17 cytokines' cross talk in the inflammatory regulation in psoriasis." (PMID 34305455, 2021).